PIK3CA (phosphatidylinositol-4,5-bisphosphate 3-kinase catalytic subunit alpha)
Diseases named in the same sentence as PIK3CA in open-access papers (continued):
Sharing a sentence is not in itself a finding about the gene and the disease.
breast cancer (continued). "At present alpelisib is not registered, nor reimbursed for the treatment of tumors other than breast cancer with PIK3CA mutations." (PMID 37086483, 2023). "PIK3CA showed the most frequent mutations in breast cancer genomes, 22 nonsilent mutations in 16 breast cancers (51.6%)." (PMID 37120792, 2023). "PIK3CA mutations were also associated with relatively low Ki-67 levels, low histological grades, and hormone receptor positivity, and relatively few TNBC-type breast cancers were reported in this group." (PMID 37747019, 2023). "Our cohort including only ER-positive, HER2-negative breast cancer patients also showed that PIK3CA mutations did not affect the response to 6 months NAE." (PMID 37106324, 2023). "To study the tumour suppressor role of KMT2C in breast cancer, we generated mouse models of Erbb2/Neu, Myc or PIK3CA-driven tumorigenesis, in which the Kmt2c locus is knocked out specifically in the luminal lineage of mouse mammary glands using the Cre recombinase." (PMID 36933062, 2023). "PIK3CA mutant ER+ breast cancers exhibit an RNA expression profile of enhanced Wnt/β-catenin signaling, including up-regulation of Wnt target genes (AXIN2, LEF1, MYCN) and other components such as transcriptional regulators (TCF7L1, TCF7L2, CTNNB1), receptors (FZD4, FZD7) and ligands (WNT5A)." (PMID 37471270, 2023). "PIK3CA act as an alpha catalytic subunit of phosphatidylinositol 3-kinase (PI3K), the activating mutations of the PIK3CA gene, which include prostate colorectal, head and neck, and breast cancers." (PMID 36865499, 2023). "A total of 19 patients (22.62%) with advanced breast cancer who received CDK4/6 inhibitors (n=84, ribociclib=47, palbociclib=32, abemaciclib=5) and 3 patients (18.75%) who received an mTOR inhibitor (n=16) were reported to have a PIK3CA mutation." (PMID 37655108, 2023). "It has also been shown that everolimus is equally active in PIK3CA wild-type and mutant types of breast cancer, which suggests that other pathways (e.g., MAPK signaling) could activate mTOR complexes even in the absence of PI3K overactivation." (PMID 37759706, 2023). "Our data confirm that the presence of PIK3CA mutations is associated with reduced sensitivity to both trastuzumab monotherapy and the dual anti-HER2 blockade with trastuzumab plus pertuzumab in HER2+ breast cancer preclinical models." (PMID 37469415, 2023). "PIK3CA gene amplification also occurs less commonly in ∼9% of breast cancers." (PMID 37471270, 2023). "For the identification of breast cancer patients who might benefit from targeted therapy with specific PIK3CA inhibitors, locally deployable highly sensitive, and specific PIK3CA mutation testing that covers all actionable mutations is required." (PMID 36367572, 2023). "A phase III randomised trial was therefore planned to evaluate alpelisib plus trastuzumab with or without fulvestrant in patients with PIK3CA-mutated HER2+ advanced breast cancer." (PMID 37489050, 2023). "Using breast cancer cell lines and xenograft models we show that RMC-6272 causes apoptosis specifically in PIK3CA and PTEN mutant ER+/HER2- breast cancer cell lines through suppression of the rapamycin resistant, mTORC1 substrate 4EBP1 and reduction of the pro-survival protein MCL1." (PMID 37264081, 2023). "Single or multiple PIK3CA mutations do not independently correlate with human breast cancer prognosis when corrected for ER-positivity or other favorable-risk variables." (PMID 37471270, 2023).
breast cancer (continued). "PIK3CA hotspot mutations (H1047R, E545K, and E542K) were found in 63.5% of premenopausal patients with breast cancer and in 56.2% of postmenopausal patients with HR+/HER2– breast cancer." (PMID 37655108, 2023). "We examined the hypothesis that PIK3CA mutations and low PTEN expression affect the response to neoadjuvant therapy and prognosis in postmenopausal luminal breast cancer patients." (PMID 37106324, 2023). "Though our data represents a relatively small cohort of tumor samples, we have found suggestive evidence that for some targeted drugs, such as PIK3CA inhibitors, there could be value in using dogs with naturally occurring mammary tumors as comparative models." (PMID 36635367, 2023). "Conversely, HS‐10352 displayed no inhibitory effects on cell lines lacking PIK3CA mutations, like the human breast cancer HDQ‐P1 cell line and the human gastric cancer SNU‐1 and MKN‐74 cell lines." (PMID 38037839, 2023). "Moreover, taselisib was equally cytotoxic toward both PIK3CA mutant breast cancer and B cells, targeting both with an IC50 around 1 nM." (PMID 36913051, 2023). "Additionally, phosphatidylinositol-4,5-bisphosphate 3-kinase (PIK3CA) mutations, abnormalities in the PI3K-AKT pathway, and a crucial gene implicated in cancer initiation and development are shared between human breast cancer and canine mammary tumors." (PMID 36900408, 2023). "E545K is one of the most common alterations of PIK3CA seen in breast cancer patients." (PMID 37096065, 2023). "PIK3CA, CCND1, and FGR1 mutations were more frequently detected in ER+ breast cancers." (PMID 36909339, 2023). "Moreover, an analysis of hotspot mutations in the genes PIK3CA, ESR1, AKT1 and ERBB2 frequently present in breast cancer was performed." (PMID 36823365, 2023). "The PIK3CA gene plays a pivotal role in the pathogenicity of breast cancer." (PMID 37821962, 2023). "In a group of patients with hereditary breast cancer, PIK3CA mutations were associated with BRCA2 but not BRCA1 mutations, and with luminal-type breast cancer." (PMID 37803017, 2023). "In vitro treatment of PIK3CA-mutant breast cancer brain metastases cell lines with GDC-0084 reduced their viability, induced apoptosis, and inhibited the phosphorylation of AKT and p70S6, highlighting its potential as a therapeutic strategy against breast cancer with brain metastases." (PMID 36671478, 2023). "Overall, these findings demonstrated that KAT7 regulates PIK3CA expression in breast cancer." (PMID 36724120, 2023). "PIK3CA is one of the most common isoforms and is found to be a dysregulated gene in breast cancer." (PMID 37821962, 2023). "In some cases, despite an international therapeutic consensus with significant evidence levels, the immune checkpoint inhibitor has not yet been approved in Japan, and there are no clinical trials on the immune checkpoint inhibitors, such as those related to PIK3CA alterations in breast cancer." (PMID 36251535, 2023). "Mutations of the PIK3CA gene, inducing hyperactivation of the alpha isoform (p110α) of PI3K, occur in 28% to 46% of patients with HR+/human epidermal growth factor receptor-2–negative (HER2–) advanced breast cancer (ABC)." (PMID 37655108, 2023). "Moreover, apoptosis of PIK3CA-mutant breast cancer brain metastatic cells was increased following the treatment in lines in a dose-dependent fashion." (PMID 37046703, 2023). "We hypothesize that the alpha-specific PI3K inhibitor alpelisib could be the best drug with which to target the PI3K pathway in order to enhance the antitumor efficacy of anti-HER2 therapy in HER2+/PIK3CA mutant breast cancer." (PMID 37469415, 2023).
breast cancer (continued). "PIK3CA gene mutations are identified in approximately 40% of ER+, HER2-negative breast cancer." (PMID 38003387, 2023). "Herein, we examined the impact of PIK3CA activating mutations on the efficacy of anti-HER2 therapies and explored the therapeutic potential of alpha-selective PI3K pharmacological inhibition in HER2+/PIK3CA mutant breast cancer using pre-clinical in vitro and in vivo models." (PMID 37469415, 2023). "Prosurvival autophagy in the process of ECM detachment in breast cancer is oncogene specific and involves a phosphatidylinositol 4,5-bisphosphate 3-kinase catalytic subunit alpha mutation but not an HRAS mutation." (PMID 36831154, 2023). ", for example, showed that nearly one-third of PIK3CA mutations identified in a cohort of HR+/HER2-breast cancer patients were not covered by the clinical trial assay." (PMID 36367572, 2023). "Approximately 40% of patients with hormone receptor (HR)‐positive and human epidermal growth factor receptor 2 (HER2)‐negative advanced breast cancer (ABC) exhibit PIK3CA mutations." (PMID 38037839, 2023). "In HR-positive, PIK3CA mutant breast cancer, clinical PI3K inhibition hyperactivates ER signaling." (PMID 37568822, 2023). "Characteristics of ER+/HER2-breast carcinoma samples included in the second PIK3CA testing round." (PMID 36825198, 2023). "Due to the absence of local validation and implementation, PIK3CA mutation testing was not routinely performed in HR+/HER2-breast carcinoma and remained largely unavailable in Portugal." (PMID 36825198, 2023). "Testing for PIK3CA mutation, germline BRCA1/2, PALB2 pathologic variant, homologous recombination deficiency (HRD), PD-L1 expression, and TMB is some of the latest developments to guide breast cancer treatment." (PMID 35884530, 2022). "Our work provides compelling evidence to support the clinical utility of PIK3CA allelic expression in breast cancer in identifying patients of poorer prognosis, and those with low expression of the mutated allele, who will unlikely benefit from PI3K inhibitors." (PMID 35676284, 2022). "Further, in a study published by Tury and colleagues, the COX-2-selective inhibitor celecoxib was effective against PIK3CA-mutated patient-derived breast cancer xenografts, but not against PIK3CA-wildtype xenografts." (PMID 35780223, 2022). "Several clinical trials are ongoing in multiple types of PIK3CA-mutated tumors, but also in PIK3CA-mutated vs. non-mutated breast cancers." (PMID 36139608, 2022). "We tested an unselected and rather large cohort of early breast cancer patients, thus we assume that our data provide a realistic view, demonstrating a lack of a general impact of PIK3CA-mutations on the course of disease in breast cancer." (PMID 36279023, 2022).
breast cancer (continued). "The present study showed that FTY720 possesses the ability to overcome resistance to trastuzumab therapy in HER2-positive breast cancer with or without PIK3CA mutation." (PMID 34997132, 2022). "PIK3CA, PIK3CB and PIK3R1 mutations are frequently detected in breast cancer." (PMID 36010585, 2022). "miR-19b-3p regulates PIK3CA and could reverse saracatinib resistance in saracatinib-resistant breast cancer cells." (PMID 35615145, 2022). "NCCN Guidelines for Breast Cancer V.1.2021 include NGS and comprehensive genomic profiling (CGP) as a method of detecting actionable mutations and fusions such as BRCA1/2 mutations, PIK3CA mutations, ESR1 mutation, HER2 mutation, MSI-H status, and deficient mismatch repair (dMMR)." (PMID 35804935, 2022). "We chose to analyze the following four TCGA datasets because PIK3CA is frequently mutated, and PIK3R2 is overexpressed in these tumor types: colorectal cancer (COAD), bladder carcinoma (BLCA), endometrial carcinoma (UCEC), and breast cancer (BRCA)." (PMID 35418124, 2022). "BAY1125976 inhibits broadly growth of human cancer cell lines and tumor xenografts, including the KPL-4 breast cancer model (PIK3CA H1074R mutant), the MCF7 and HBCx-2 breast cancer models, the Akt E17 K mutation-driven prostate cancer (LAPC-4) and anal cancer (AXF984) model." (PMID 36180910, 2022). "Studies have demonstrated that the gain‐of‐function mutation in PIK3CA (the gene encoding p110α, the catalytic subunit) is associated with the overactivation of PI3K, which is an effective mechanism of oncogenesis, especially in breast cancer." (PMID 38089455, 2022). "The most common PIK3CA mutations, PIK3CAH1047R and PIK3CAE545K, are gain-of-function mutations that promote constitutive PI3Kα activation in the absence of growth factor stimulation and cause de novo murine mammary tumor formation." (PMID 36612130, 2022). "We previously generated and validated MCF-7 and T47D human immortalized PIK3CA-mutant ER+ breast cancer cell lines with stable ectopic GFP-INPP4B overexpression, in order to model the effects of increased INPP4B expression as we described in a subset of ER+ breast tumors." (PMID 36612130, 2022). "The good performance obtained illustrates that the differences in breast morphology and other features resulting from microstructural changes in PIK3CA mutant breast cancers could be captured by US images and identified using a deep learning model." (PMID 35719907, 2022). "The therascreen PIK3CA RGQ PCR Kit is a real-time qualitative in vitro diagnostic PCR detection, which can detect 11 mutations of PIK3CA gene intissues or plasma of patients with breast cancer." (PMID 35735625, 2022).